MTMR7 (myotubularin related protein 7)
Description:
Lipid phosphatase that specifically dephosphorylates the D-3 position of phosphatidylinositol 3-phosphate (PtdIns(3)P) and inositol 1,3-bisphosphate (Ins(1,3)P2).
Tractability: Antibody: UniProt places it where antibodies can reach, with medium confidence. PROTAC: ubiquitination databases record sites on it; its protein half-life has been measured.
Gene: Protein-coding gene on chromosome 8 (17,296,794 to 17,413,528, reverse strand). Ensembl gene ENSG00000003987.
Subcellular location: Cytoplasm; Endomembrane system
Subcellular location (Human Protein Atlas): Cytosol; Nucleoplasm
Pathways (Reactome):
Metabolism: Synthesis of IP2, IP, and Ins in the cytosol; Synthesis of PIPs at the late endosome membrane
Gene Ontology:
Molecular function: protein binding; inositol bisphosphate phosphatase activity; phosphatidylinositol-3,5-bisphosphate 3-phosphatase activity; phosphatidylinositol-3-phosphate phosphatase activity; protein tyrosine phosphatase activity; phosphatidylinositol phosphate phosphatase activity
Biological process: phosphatidylinositol biosynthetic process; phosphatidylinositol dephosphorylation; protein dephosphorylation
Cellular component: cytoplasm; cytosol; endomembrane system; membrane
Genetic constraint (gnomAD): Loss-of-function variants: 70 observed, 76.19 expected, observed/expected ratio (o/e) 0.92, 90% interval 0.76 to 1.12. The synonymous counts are far from expectation, so gnomAD's model fits this gene poorly and the ratio says little. Missense variants: 1,002 observed, 827.52 expected, observed/expected ratio (o/e) 1.21, 90% interval 1.15 to 1.28. Synonymous variants: 364 observed, 297.09 expected, observed/expected ratio (o/e) 1.23, 90% interval 1.12 to 1.34.
Homologues: Orthologues: chimpanzee MTMR7 (99% identical), macaque MTMR7 (99% identical), dog MTMR7 (96% identical), rabbit MTMR7 (96% identical), pig MTMR7 (95% identical), mouse Mtmr7 (95% identical), rat Mtmr7 (93% identical), guinea pig MTMR7 (90% identical), tropical clawed frog mtmr7 (80% identical), zebrafish mtmr7a (64% identical), zebrafish mtmr7b (57% identical), Drosophila melanogaster Mtmr6 (48% identical), and 11 more. Paralogues in human: MTMR6 (55% identical), MTMR8 (52% identical), MTMR2 (32% identical), MTM1 (32% identical), MTMR1 (31% identical), MTMR3 (31% identical), MTMR4 (29% identical), MTMR9 (28% identical), SBF1 (28% identical), SBF2 (27% identical), MTMR12 (18% identical), MTMR10 (18% identical), and 1 more.
Diseases named in the same sentence as MTMR7 in open-access papers:
MTMR7 is named in the same sentence as 14 diseases in open-access papers, as found by Europe PMC text mining. Sharing a sentence is not in itself a finding about the gene and the disease. The quoted sentences say what the papers report.
colorectal cancer (5 papers, 2016 to 2023). A primary or metastatic malignant neoplasm that affects the colon or rectum. "Mutation of myotubularin-related protein 7 gene (MTMR7) has been described as contributing to colorectal cancer (CRC) development." (PMID 37892232, 2023). "In colorectal cancer, down-regulation of MTMR7 was associated with a malignant phenotype by reducing the level of phosphoinositide and the activity of insulin-mediated AKT-ERK1/2 signaling." (PMID 32701143, 2020). "In human colorectal cancers, MTMR7 has been down-regulated, which has been related to a poor prognosis." (PMID 37892232, 2023). "MTMR7 protein was down‐regulated with increasing tumour grade and stage in colorectal cancer, while PIK3CB30 and UGCG31, 32 preferentially up‐regulate and promote cancer progression." (PMID 31475440, 2019). "Mechanically, MTMR7 inhibits insulin-mediated AKT-ERK1/2 signaling, which in turn decreases colorectal cancer cell proliferation." (PMID 33282950, 2020). "We show that MTMR7 protein was down-regulated with increasing tumor grade (G), size (T) and stage (UICC) in patients with colorectal cancer (CRC) (n=1786)." (PMID 27409167, 2016). "Myotubularin-related protein 7 (MTMR7) is downregulated in colorectal cancer and is a negative predictor of colorectal cancer patient survival." (PMID 33282950, 2020).
Creutzfeldt-Jakob disease (2 papers, 2019 to 2021). "The top hit in our GWAS resided in MTMR7, which is ubiquitously expressed in the brain and contains a different SNP previously associated with susceptibility to Creutzfeldt-Jakob disease." (PMID 33757599, 2021). "An intronic variant was identified in the genetic locus of myotubularin related protein 7 (MTMR7), a 3-phosphatase dephosphorylating PI3P and inositol 1,3-bisphosphate and linked to variant Creutzfeldt-Jakob disease susceptibility." (PMID 31507376, 2019).
endometriosis (1 paper, 2020). The growth of functional endometrial tissue in anatomic sites outside the uterine body. "Of the previously reported variants associated with endometriosis, most had the directionally concordant effect except for rs1250241, chr2:g.216 295312 T > A at 2q35, FN1, rs517875, chr3:g.174350886 C > A at 3q13, RAP1BP2, and rs13271465, chr8:g.17282411 T > C at 8p22, MTMR7/ADAM24P." (PMID 31488892, 2020).
osteosarcoma (1 paper, 2019). A usually aggressive malignant bone-forming mesenchymal neoplasm, predominantly affecting adolescents and young adults. "CDKN2A/B and MTMR7 contribute to osteosarcoma risk in our modeling studies, and IGF1 does so by proxy with size." (PMID 30890123, 2019). "Thus CDKN2A/B, IGF1 and the two single candidates at their loci – MTMR7, FGF9 – seem likely to be associated with canine osteosarcoma risk." (PMID 30890123, 2019).
type 2 diabetes mellitus (1 paper, 2016). A type of diabetes mellitus that is characterized by insulin resistance or desensitization and increased blood glucose levels. "Insulin reduced MTMR7 protein levels in human CRC cell lines, and CRC patients with type 2 diabetes mellitus (T2DM) or loss of imprinting (LOI) of insulin-like growth factor 2 (IGF2) had an increased risk for MTMR7 loss." (PMID 27409167, 2016). "To identify factors which influence MTMR7 expression, we analysed a second independent cohort of CRC patients with metabolic parameters known to activate RTK signaling: type 2 diabetes mellitus (T2DM) and loss of imprinting (LOI) of the IGF2 gene in the tumor." (PMID 27409167, 2016).
variant Creutzfeldt-Jakob disease (1 paper, 2024). A form of Creutzfeldt-Jakob disease that is most commonly contracted after consuming meat from an animal suffering from bovine spongiform encephalopathy. "In addition, a relatively rare SNP variant (rs4921542) in the intron region of MTMR7 is associated with a high risk of variant Creutzfeldt-Jakob disease (vCJD)." (PMID 38529329, 2024).
tumor (5 papers, 2016 to 2021). "IGF2 LOI (n=13) was associated with a higher risk for loss of MTMR7 in the tumor (OR: 13.71, *p= 0.0157) compared with the control group of CRC cases with neither IGF2 LOI nor T2DM (n=16)." (PMID 27409167, 2016). "MTMR7 positivity in tumor cells was negatively associated with local tumor growth (T1/2 vs. T3/4: *p=0.003), tumor stage (UICC I-IV: *p=0.027) and grade (G: *p=0.015)." (PMID 27409167, 2016). "Regarding prognostic relevance, we found that MTMR7 positivity in the stroma tissue surrounding the tumor cells was associated with a reduced 5- and 10-year survival rate for patients with CRC in the UICC stage 1." (PMID 27409167, 2016). "Thus, loss of endogenous MTMR7 protein resulted in increased tumor cell proliferation, consistent with the observation that MTMR7 was down-regulated during CRC progression in patients." (PMID 27409167, 2016). "The positive association of stromal MTMR7 with poor survival in UICC stage I CRC patients may implicate tumor-stroma interactions via secreted growth factors." (PMID 27409167, 2016). "The results confirmed that the numbers of methylated CG sites in DPP6 and MTMR7 in tumor tissues were significantly higher than in normal tissues (7.43 ± 6.12 vs. 2.78 ± 2.96, P<0.001; 45.95 ± 16.68 vs. 31.36 ± 16.90, P<0.001)." (PMID 32701143, 2020). "The here described MTMR7-PPARγ interaction complex offers a novel mode of PPARγ regulation by compartmentalization and a possible explanation for the pro- vs. anti-tumour effects of PPARγ-agonists." (PMID 32522977, 2020). "MTMR7 mRNA was also detected in frozen samples of normal colon (NC) and tumor (TU) tissues from CRC patients and in mouse organs." (PMID 27409167, 2016). "Consistent with the findings on MTMR7 mRNA expression, MTMR7 protein was lost in 77.5 % (n=1776) of tumor and 35.4 % (n=1786) of stroma samples." (PMID 27409167, 2016). "MTMR7 was lost to a higher percentage in tumor tissues of both patient groups (T2DM: 88%, 15 of 17; IGF2 LOI: 92%, 12 of 13) than in individuals with neither T2DM nor IGF2 LOI (44%, 7 of 16)." (PMID 27409167, 2016). "Instead, MTMR7 was strongly present in smooth muscle cells of the tumor-stroma." (PMID 27409167, 2016). "However, MTMR7 expression was higher in the distal colon (sigmoid and rectum) than in the proximal colon (coecum and ascending colon) both in tumor and stroma (*p<0.001)." (PMID 27409167, 2016). "More than 65 % of stroma tissue adjacent to the tumor still expressed MTMR7 protein." (PMID 27409167, 2016). "Thus, future pre/clinical studies have to explore the function of MTMR7 in the tumor microenvironment and its potential as a marker or drug target in human CRC." (PMID 27409167, 2016). "Thus, loss of MTMR7 did not occur before or during tumor initiation but rather at a later step of tumor progression." (PMID 27409167, 2016). "BSP was performed focusing on the promoter regions of four potential PMDGs (DPP6, HIST1H4E, MTMR7, and ZFP28) in 72 paired tumor and adjacent normal samples of PDAC patients." (PMID 32701143, 2020). "The overall alteration rate of MTMR7 and MTMR9 genes was <10% in 86 cancer studies from >15 different tumor entities, indicating that the two genes are of importance beyond CRC." (PMID 27409167, 2016). "Expression of MTMR7 in the tumor was independent of prognosis, whereas stromal MTMR7 predicted poor survival in CRC patients." (PMID 27409167, 2016). "The presence of MTMR7 in the stroma correlated with poor prognosis, whereas MTMR7 expression in the tumor was not predictive for patients' survival." (PMID 27409167, 2016). "The negative correlation between MTMR7 positivity and tumor grade was confirmed: 64 % (7 of 11) of G1 tumors were positive for MTMR7, in contrast to 47 % (33 of 70) of G2 tumors and 32 % (8 of 25) of G3 tumors." (PMID 27409167, 2016). "No prognostic relevance was found for expression of MTMR7 protein in the tumor." (PMID 27409167, 2016). "MTMR7 was present in human CRC tumor cells or completely absent." (PMID 27409167, 2016).
tumor (continued). "In stroma cells surrounding the tumor with high levels of MTMR7, AMPK may thereby evoke metabolic adaptation to lack of nutrients or oxygen that promotes tumor growth and confers poor prognosis for the patient." (PMID 27409167, 2016).
cancer (3 papers, 2016 to 2020). A tumor composed of atypical neoplastic, often pleomorphic cells that invade other tissues. "Synthetic peptides were designed resembling the regulatory coiled-coil (CC) domain of MTMR7, and their activities studied in human cancer cell lines and C57BL6/J mice." (PMID 32522977, 2020). "Mining of the human cancer cell line encyclopedia (CCLE) data base evinced alterations of MTMR7 in 11% and of MTMR9 in 16% of cell lines (n=1019) (data not shown)." (PMID 27409167, 2016). "Thus, MTMR7 is a positive regulator of PPARγ, and its mimicry by synthetic peptides overcomes inhibitory mechanisms active in cancer cells possibly contributing to the failure of clinical studies targeting PPARγ." (PMID 32522977, 2020). "Thus, PPARγ-agonist facilitates nuclear accumulation of MTMR7 in vitro and ex vivo in patient-derived cancer stem cells." (PMID 32522977, 2020). "Collectively, these data indicated that insulin down-regulates MTMR7 protein as an endogenous inhibitor of growth factor receptor signaling, thereby establishing a potential vicious cycle promoting the proliferation of cancer cells." (PMID 27409167, 2016). "MTMR7 provides a novel link between growth factor signaling and cancer, and may thus constitute a potential marker or drug target for human CRC." (PMID 27409167, 2016). "RT-qPCR analyses showed that MTMR7 mRNA was present in six human CRC cell lines (SW480, HCT116, Caco2, HT29, LOVO, DLD1) and in non-cancer HEK293T cells." (PMID 27409167, 2016). "However, the function of myotubularin-related protein 7 (MTMR7) in cancer is unknown." (PMID 27409167, 2016).
cardiovascular diseases (1 paper, 2024). "So, MTMR7 may be a potential research target linking vCJD and cardiovascular disease." (PMID 38529329, 2024). "Therefore, further efforts are needed to investigate whether MTMR7 can function in cardiovascular diseases via affecting PPARγ." (PMID 38529329, 2024). "MTMR7 can interact with PPAR, which indirectly indicates that MTMR7 regulates cardiovascular disease by regulating metabolism." (PMID 38529329, 2024).
MTMR7 also shares sentences with these, for which no sentence is quoted: cerebrovascular disease (1 paper); leiomyoma (1); leiomyosarcoma (1); Myotubular myopathy (1); renal carcinoma (1).